INS (insulin)
Diseases named in the same sentence as INS in open-access papers (continued):
Sharing a sentence is not in itself a finding about the gene and the disease.
diabetes (continued). "In 1994, Chen H and colleagues first reported the application of auricular pressure in patients with diabetes in a clinical trial, finding that auricular pressure promoted insulin secretion and lowered blood glucose in patients with diabetes." (PMID 39301316, 2024). "The occurrence of type 2 diabetes mellitus (T2DM), a worldwide chronic disease, is mainly caused by insufficient insulin production and places a huge burden on the health system." (PMID 39408825, 2024). "Insulin resistance leads to increased fasting blood glucose and pre-diabetes (impaired glucose tolerance), with a progressive decline in both insulin secretion and insulin sensitivity." (PMID 38233797, 2024). "Insulin pumps, a cornerstone of modern diabetes management, provide greater flexibility in insulin delivery compared to traditional injection methods." (PMID 38882982, 2024). "Type 2 diabetes mellitus (T2DM) refers to a type of diabetes mellitus with insulin resistance with progressive insulin secretion insufficiency as the main etiology." (PMID 39267858, 2024). "Insulin pumps can provide users with a safer and more comfortable alternative for managing diabetes through effectively tackling these practical issues." (PMID 39065641, 2024). "Understanding the experiences of older people when they transition to insulin will help the development of healthcare interventions to enhance their diabetes outcomes, overall health and quality of life." (PMID 38778253, 2024). "Connected insulin pens are creating opportunities for the millions of individuals with diabetes using multiple daily injections (MDI) therapy across the globe." (PMID 37855818, 2024). "Annual diabetes treatment costs vary widely, ranging from $15 to over $500 for medications alone, with insulin prices differing substantially." (PMID 39803007, 2024). "Both insulin sensitivity and insulin resistance are significant factors in the development and management of diabetes." (PMID 38711066, 2024). "For example, in the case of the PWD with diabetes mellitus, diet restriction, frequent blood glucose checks, and insulin injections intensified behavioral symptoms that led to aggression toward his caregiver." (PMID 38525750, 2024). "Insulin resistance and impaired insulin secretion are key mechanisms in the development of hyperglycemia and diabetes." (PMID 39480760, 2024). "Antidiabetic drugs such as insulin, metformin, repaglinide and acarbose are available to reduce, control and manage diabetes mellitus by working on these mechanisms." (PMID 39458809, 2024). "These disruptions reduce the production of short-chain fatty acids crucial for insulin sensitivity, further contributing to the development of metabolic disorders like type 2 diabetes mellitus." (PMID 39449954, 2024). "And yes, I have needed to go often for medicines for people who has diabetes, to bring insulin pens, or medicines for persons who have seizures, or for constipation, they only give me their prescriptions and I go and buy them there." (PMID 39565734, 2024). "In conclusion, the results demonstrate in INS-1 β-cells that hyperglycemic conditions, like those present in diabetes mellitus, potentiated the effects of ucOC on intracellular calcium signaling and insulin secretion." (PMID 39125265, 2024). "Our study aimed to assess the potential correlation between lipohypertrophy and glycemic control, as well as insulin dosing in patients with diabetes." (PMID 38215209, 2024). "Type 2 diabetes mellitus is a complex metabolic disorder characterized by insulin resistance and, subsequently, decreased insulin secretion." (PMID 39518420, 2024). "GNAS is important for β-cell insulin secretion, with reduced expression observed in pancreatic islets from individuals with type 2 diabetes and in urine from individuals with diabetes." (PMID 38904047, 2024). "Diabetes is marked by increased hepatic glucose output, insulin resistance, and insufficient insulin secretion." (PMID 39588337, 2024).
diabetes (continued). "Previous studies have shown that in a population with normal blood glucose levels females are more insulin sensitive than males, although this sex advantage disappears in females with diabetes." (PMID 38218814, 2024). "Diabetes, a metabolic disorder resulting from insufficient insulin secretion or abnormal cellular response to insulin, is increasingly prevalent." (PMID 39593713, 2024). "In participants with diabetes, heart failure, falls, amputation, and receipt of insulin treatment increased the odds of hospitalization over time." (PMID 39058533, 2024). "Multiple retrospective chart reviews have suggested the same trend of improved diabetes control and/or decreasing insulin needs in patients with type 2 diabetes receiving TKIs." (PMID 39659385, 2024). "Type 1 diabetes mellitus, or insufficient insulin synthesis by the pancreas, or Type 2 diabetes mellitus, or insufficient insulin production in the face of insulin resistance, can both result in hyperglycemia." (PMID 38312640, 2024). "Different types of medications are available for obesity (orlistat, sibutramine, etc.)and diabetes (biguanides, sulfonylurea, thiazolidinedione, insulin, etc.)." (PMID 38543143, 2024). "In T2D, there is an inverse relationship between IGFBP-1 and insulin however, a parallel upward shift in the regression line is observed, compared to pre-diabetes." (PMID 39595651, 2024). "The incorporation of pulses possessed hypoglycemic effects, resulting in a significant decrease in glucose level and increase in insulin level, which endorsed the modulatory effect of designer biscuits for diabetes mellitus." (PMID 38559441, 2024). "FAHFA is an endogenous lipid that promotes glucose transport and secreted insulin, which had a preventive effect on diabetes." (PMID 38413895, 2024). "Studies have shown that acupuncture can improve obesity and insulin sensitivity in patients with type 2 diabetes and has a certain therapeutic effect on diabetes." (PMID 38312234, 2024). "In patients with postsurgical diabetes mellitus, insulin treatment by conventional or pump therapy similar to children with type 1 diabetes mellitus is necessary to achieve optimal glycemic control." (PMID 37454648, 2024). "Patients with type 2 diabetes mellitus (T2DM) who underwent intensification for at least 3 months from human to analogue insulin were included in this study." (PMID 38694591, 2024). "Oral pathogens exacerbate diabetes through systemic inflammation, impaired insulin sensitivity, and direct effects on glycemic control." (PMID 39770344, 2024). "It is primarily classified into two types: type 1 diabetes, which requires insulin administration and accounts for 5–10% of cases; and type 2 diabetes, an insulin-independent form affecting up to 90% of individuals with diabetes." (PMID 39766390, 2024). "There are several barriers to optimising glycaemia in T1D, including integrating diabetes management into day‐to‐day life, fear of hypoglycaemia, insulin dose calculation, as well as the inconvenience of frequent self‐monitoring of blood glucose (SMBG) levels." (PMID 38268307, 2024). "Most people with diabetes used insulin (n=165, 22.8%), metformin (n=318, 43.9.1%), or both (n=59, 8.1%)." (PMID 38412008, 2024). "STZ‐induced type I diabetes mellitus (DM) models have been developed in rodents for decades by depleting the insulin‐producing β‐cells in the pancreas, thereby causing hyperglycemia with a low insulin level." (PMID 39350510, 2024). "Although she was not receiving any blood glucose-lowering agents, her mother and all her maternal uncles were diabetic and under insulin treatment due to an early diagnosis of diabetes." (PMID 39191897, 2024). "An article published in 2003 found that individuals who were on insulin had significant knowledge gaps about diabetes." (PMID 39273732, 2024).
diabetes (continued). "There were 107 patients (62.9%) who consulted a specialist diabetes endocrinology department preoperatively and 118 patients (69.4%) who required sliding-scale insulin during the perioperative period." (PMID 38915109, 2024). "The rapid and pulsatile interplay of glucagon and insulin in the fasting state has been elaborated by Nauck and Meier in healthy people and in prediabetes or diabetes." (PMID 38579770, 2024). "Previous studies have shown that expression of PDX1 in the liver via adenovirus vectors can produce some insulin‐expressing cells in the liver and alleviate symptoms of diabetes in animal models." (PMID 38599852, 2024). "An excess of glucagon relative to insulin characterizes the metabolic dysregulation and hyperglycemia of diabetes." (PMID 39619323, 2024). "Both experimental and clinical data indicate that inappropriate interactions of AVP and insulin play an important role in the development of insulin resistance in obesity and diabetes mellitus." (PMID 39769071, 2024). "The evidence regarding the impact of lupeol on the survival of β-cells can be categorized into two broad groups: the trials conducted on isolated islets or insulin-secreting cell lines in vitro; and the studies carried out on live animal models of diabetes." (PMID 39605919, 2024). "Patients who experienced new-onset DR at follow-up tended to be female, younger, with a longer duration of diabetes, on insulin, and had higher HbA1c and greater visceral obesity at baseline than their counterparts." (PMID 38319705, 2024). "Beyond the role of JAK/STAT signaling and insulin resistance, in pathologies such as cancer and diabetes, these evolutionary preserved signaling pathways are essential for the wellbeing of the organism." (PMID 38566182, 2024). "Intermittently Scanned Continuous Glucose Monitoring (isCGM) devices are increasingly being used in patients with type 2 diabetes mellitus (T2DM) on insulin therapy for their benefits regarding disease management." (PMID 38337336, 2024). "Dipeptidyl peptidase-4 (DPP-4) inhibitors are a class of drugs that enhance the incretin-insulin pathway and offer effective glycemic control in type 2 diabetes mellitus." (PMID 38523307, 2024). "In fact, while insulin treatment has become increasingly essential for patients living with diabetes over the past few decades, insulin-derived amyloidosis (AIns) is a skin complication of insulin therapy." (PMID 39858435, 2024). "Management of the patient included diabetes education, optimizing insulin therapy, nutritional support, and closely monitoring labs in a multi-disciplinary approach." (PMID 39156415, 2024). "Our results showed that serum c-peptide levels decreased when diabetes was induced in rats, as we also reported a significant decrease in serum insulin levels earlier." (PMID 39337311, 2024). "The primary treatment regimen for the management of diabetes still remains the oral hypoglycemic drugs along with insulin injections." (PMID 38255714, 2024). "Polyphenols are known for their antioxidant and anti-inflammatory properties and have shown promise in modulating glucose metabolism and improving insulin sensitivity – making them attractive candidates for diabetes management." (PMID 39822379, 2024). "This form of diabetes originates from two primary issues related to insulin: insulin resistance and dysfunction of β-cells." (PMID 38611884, 2024). "Diabetes mellitus is a chronic metabolic disorder characterized by elevated blood glucose levels resulting from insufficient insulin production or the body's inability to utilize insulin effectively." (PMID 38646317, 2024). "Fasting insulin and C-peptide are 321.6 pmol/l and 754 pmol/l at 21 years on from her diabetes diagnosis." (PMID 38461278, 2024). "Diabetes is a disorder of glucose regulation due to insufficient insulin secretion and insulin resistance, in which inflammation and oxidative stress also have long been considered the main components of pancreatic β-cell failure." (PMID 39647865, 2024).
diabetes (continued). "Not only that, insulin target tissues such as adipose tissue, liver, muscle, and pancreatic islets are under attack from chronic inflammation in children with obesity and diabetes." (PMID 38784180, 2024). "Diabetes affects antibody response to SARS-CoV-2 vaccination mainly among the elderly under insulin treatment and often affected also by other important co-morbidities." (PMID 39340080, 2024). "Of particular concern, countries which reported decreases in insulin availability in the public sector pharmacies in 2021were among those noted to have the greatest increases in diabetes and DKD mortality." (PMID 38205867, 2024). "Patients with inadequately controlled diabetes had the longest time to target glucose, the most insulin dose to target glucose and the most cumulative insulin requirement to maintain target glucose during the 48 h after ROSC." (PMID 38330019, 2024). "Type 2 Diabetes Mellitus (T2DM) is a metabolic condition that causes hyperglycemia due to insulin resistance and inadequate insulin production." (PMID 39599721, 2024). "The ability of CGMs to capture these fluctuations can aid in the adjustment of diet, time of dialysis, exercise, diabetes medications and especially insulin dosing." (PMID 39112642, 2024). "Since the early 1900's, there has been interest in understanding the physiology of exercise in helping people with diabetes to regulate blood glucose and improve insulin sensitivity." (PMID 39295999, 2024). "One third of those with newly diagnosed diabetes are women of reproductive age, so more data regarding the role of diabetes technology vs non-insulin pharmacotherapy before and during pregnancy are urgently needed." (PMID 38967667, 2024). "Lipodystrophy is a common complication of a subcutaneous insulin injection in patients with diabetes mellitus, with prevalence estimated at 41.8%." (PMID 39691127, 2024). "As a mitochondrial transcription factor, TFB1M can regulate mitochondrial DNA transcription and repair, thereby protecting mitochondrial function and improving energy metabolism and insulin secretion in diabetes." (PMID 38809515, 2024). "In the case of women with PCOS, the impacts of factors faced by patients, such as high triglyceride, fasting glucose, and insulin levels, metabolic disorders, or diabetes, on the composition and changes in the microbiome and the role of Lactobacillus spp." (PMID 38396443, 2024). "HbA1c, insulin delivery method, satisfaction with diabetes management, dietary habits, physical activity level, depression, anxiety, and telehealth vs. in-person appointments." (PMID 39867016, 2024). "Research indicates that iron directly impacts glucose metabolism, especially in patients with diabetes, where low iron levels correlate with decreased insulin sensitivity." (PMID 39839287, 2024). "Currently, innovation is aimed at more personalized and convenient insulin therapies, catering to the diverse needs of individuals managing diabetes." (PMID 38542928, 2024). "There were 31,019 (77.3%) patients who controlled their diabetes with oral agents, 4691 (12.6%) with insulin, and 4419 (10.1%) with diet." (PMID 39272776, 2024). "The introduction of light-activated insulin changes how diabetes is treated, providing several notable benefits compared to conventional methods of administering insulin via injections or oral medications." (PMID 38542928, 2024). "Banting’s work led to the groundbreaking discovery of insulin, which revolutionized diabetes management by enabling patients to effectively regulate their blood sugar levels for the first time." (PMID 39691108, 2024). "As the liver plays a key role in maintaining glucose homeostasis, maintaining hepatic insulin sensitivity is considered even more important for managing diabetes." (PMID 39056667, 2024). "The pathogenesis of type 2 diabetes mellitus (T2DM) is characterized by inadequate β-cell function leading to insufficient insulin secretion." (PMID 39000700, 2024).
diabetes (continued). "First, this is the first randomized controlled trial with a substantial sample size to evaluate the efficacy of a structured exercise program in improving insulin resistance and quality of life in individuals with type 2 diabetes mellitus (T2DM)." (PMID 38771888, 2024). "Many researchers have conducted extensive studies on type 2 diabetes and demonstrated the close relationship between diabetes mellitus and insulin levels." (PMID 38893405, 2024). "Wearable artificial pancreas systems have revolutionized diabetes management by integrating continuous glucose monitoring with insulin pumps to automate blood glucose control." (PMID 39006724, 2024). "It significantly affects glucose metabolism as well as tissue sensitivity to insulin, acting as a protective factor in the development of diabetes complications." (PMID 38250713, 2024). "Lifestyle changes such as diet and exercise can mitigate insulin-induced weight gain, especially in patients with diabetes who are already overweight." (PMID 39629047, 2024). "In 1922, insulin was successfully used for the treatment of diabetes, with initial preparations being derived from animal sources, primarily bovine and porcine pancreas." (PMID 39734941, 2024). "Other possible causes include genetic predisposition, duration of diabetes, and use of continuous subcutaneous insulin infusion (CSII) instead of multiple daily injections (MDIs) of insulin." (PMID 39274516, 2024). "Since thermogenic adipose tissue increases insulin sensitivity and energy expenditure to suppress the development of diabetes and obesity, there are currently numerous efforts to find therapeutic approaches to induce the formation of beige adipose tissue." (PMID 38565851, 2024). "Furthermore, insulin therapy for diabetes may alter levels of certain biomarkers associated with bone metabolism, such as advanced glycation end products and other indicators related to bone density and fracture risk, thereby influencing the processes of bone formation and resorption." (PMID 39309475, 2024). "For instance, pectin derived from red chili fruit waste has been shown to significantly improve insulin sensitivity and lower blood glucose levels in diabetes models." (PMID 39458444, 2024). "The algorithm identifies several risk factors related to developing DFUs as long-term diabetes, insulin therapy, male gender, advanced age, smoking, drug addiction, family history of diabetes, higher BMI, physical inactivity, and diabetic complications." (PMID 38182645, 2024). "As insulin production is reduced or impaired in patients with diabetes mellitus, there is a marked reduction in the presence of NO in this population." (PMID 38793985, 2024). "Recent studies have uncovered that they act as signaling molecules, influencing glucose metabolism and insulin sensitivity, thus having an impact on the development of diabetes." (PMID 38791370, 2024). "Ensuring broad accessibility will be crucial for effectively implementing light-activated insulin as a regular treatment method in diabetes care." (PMID 38542928, 2024). "Glucose uptake, insulin signaling, glycogen synthesis, and gluconeogenesis are the mechanisms involved in the pathophysiology of diabetes that are affected by TG metabolites." (PMID 38892574, 2024). "We found that although total RyR2 remained significantly unchanged, phosphorylation of RyR2 at Ser2808 increased significantly during diabetes, and these increases were attenuated by insulin and Rb1 treatment." (PMID 38961333, 2024). "Improvements in lifestyle habits and insulin replacement therapy are typical measures utilized for the treatment of diabetes." (PMID 39684854, 2024). "They believe that taking insulin helps to prevent complications of diabetes, taking insulin helps to improve their health, taking insulin helps to maintain good control of blood glucose, and taking insulin helps to improve their energy level." (PMID 39453515, 2024).